DAPK3 (death associated protein kinase 3)
Description:
Serine/threonine kinase which is involved in the regulation of apoptosis, autophagy, transcription, translation and actin cytoskeleton reorganization. Involved in the regulation of smooth muscle contraction. Regulates both type I (caspase-dependent) apoptotic and type II (caspase-independent) autophagic cell deaths signal, depending on the cellular setting. Involved in regulation of starvation-induced autophagy. Regulates myosin phosphorylation in both smooth muscle and non-muscle cells. In smooth muscle, regulates myosin either directly by phosphorylating MYL12B and MYL9 or through inhibition of smooth muscle myosin phosphatase (SMPP1M) via phosphorylation of PPP1R12A; the inhibition of SMPP1M functions to enhance muscle responsiveness to Ca(2+) and promote a contractile state. Phosphorylates MYL12B in non-muscle cells leading to reorganization of actin cytoskeleton. Isoform 2 can phosphorylate myosin, PPP1R12A and MYL12B. Overexpression leads to condensation of actin stress fibers into thick bundles. Involved in actin filament focal adhesion dynamics. The function in both reorganization of actin cytoskeleton and focal adhesion dissolution is modulated by RhoD. Positively regulates canonical Wnt/beta-catenin signaling through interaction with NLK and TCF7L2. Phosphorylates RPL13A on 'Ser-77' upon interferon-gamma activation which is causing RPL13A release from the ribosome, RPL13A association with the GAIT complex and its subsequent involvement in transcript-selective translation inhibition. Enhances transcription from AR-responsive promoters in a hormone- and kinase-dependent manner. Involved in regulation of cell cycle progression and cell proliferation. May be a tumor suppressor.
Synonyms: Dlk; ZIPK; ZIP
Tractability: Small molecule: a structure with a bound ligand is known; a high-quality ligand is known; it has a high-quality binding pocket; it belongs to a druggable protein family. PROTAC: ubiquitination databases record sites on it; its protein half-life has been measured; a small molecule that binds it is known.
Target class: CAMK protein kinase group; Kinase; CAMK protein kinase DAPK family; Protein Kinase; Enzyme
Gene: Protein-coding gene on chromosome 19 (3,958,453 to 3,971,123, reverse strand). Ensembl gene ENSG00000167657.
Subcellular location: Nucleus; Nucleus, PML body; Cytoplasm, cytoskeleton, microtubule organizing center, centrosome; Chromosome, centromere; Cytoplasm; Cytoplasm, cytoskeleton, spindle; Midbody; Nucleus (Isoform 1); Nucleus (Isoform 2)
Subcellular location (Human Protein Atlas): Cytosol; Nucleoplasm; Primary cilium; Vesicles
Pathways (Reactome):
Programmed Cell Death: Caspase activation via Dependence Receptors in the absence of ligand
Gene Ontology:
Molecular function: ATP binding; identical protein binding; leucine zipper domain binding; protein binding; protein homodimerization activity; protein kinase activity; protein serine kinase activity; protein serine/threonine kinase activity; small GTPase binding; cAMP response element binding protein binding
Biological process: apoptotic process; cellular response to type II interferon; intracellular signal transduction; negative regulation of translation; positive regulation of apoptotic process; positive regulation of canonical Wnt signaling pathway; protein autophosphorylation; protein phosphorylation; regulation of actin cytoskeleton organization; regulation of focal adhesion assembly; regulation of mitotic cell cycle; regulation of apoptotic process; regulation of autophagy; regulation of cell motility; regulation of DNA-templated transcription; regulation of mitotic nuclear division; regulation of smooth muscle contraction; positive regulation of cell migration; regulation of cell shape; regulation of myosin II filament organization
Cellular component: chromosome, centromeric region; cytoplasm; cytosol; midbody; nucleoplasm; nucleus; spindle; centrosome; PML body
Genetic constraint (gnomAD): Loss-of-function variants: 15 observed, 19.54 expected, observed/expected ratio (o/e) 0.77, 90% interval 0.51 to 1.18. The synonymous counts are far from expectation, so gnomAD's model fits this gene poorly and the ratio says little. Missense variants: 557 observed, 528.14 expected, observed/expected ratio (o/e) 1.05, 90% interval 0.98 to 1.13. Synonymous variants: 304 observed, 232.13 expected, observed/expected ratio (o/e) 1.31, 90% interval 1.19 to 1.44.
Homologues: Orthologues: chimpanzee DAPK3 (100% identical), dog DAPK3 (95% identical), pig DAPK3 (94% identical), guinea pig DAPK3 (94% identical), mouse Dapk3 (84% identical), rat Dapk3 (83% identical), zebrafish dapk3 (80% identical), tropical clawed frog dapk3 (79% identical). Paralogues in human: DAPK1 (62% identical), DAPK2 (50% identical), MYLK (33% identical), NEXN (15% identical).
Diseases named in the same sentence as DAPK3 in open-access papers:
DAPK3 is named in the same sentence as 57 diseases in open-access papers, as found by Europe PMC text mining. Sharing a sentence is not in itself a finding about the gene and the disease. The quoted sentences say what the papers report.
gastric cancer (10 papers, 2012 to 2023). A primary or metastatic malignant neoplasm involving the stomach. "The tumor-suppressor roles of Death associated protein kinase 3 (DAPK3) in gastric cancer are associated with increased ULK1 activity and autophagy." (PMID 35393404, 2022). "DAPK3 was found to be frequently mutated in gastric carcinoma." (PMID 36802409, 2023). "Down-regulation of DAPK3 was seen in 111 of 162 gastric cancer cases, and this correlated with invasion, metastasis and poorer prognosis." (PMID 27126362, 2016). "The downregulation of DAPK3 in gastric cancer patients is related to poor prognosis." (PMID 37143582, 2023). "In EBV+ gastric carcinoma, the anti-tumor effects of DAPK3 may be even more limited given that BPLF1 would counteract DAPK3-mediated STING activation." (PMID 36802409, 2023). "Death-associated protein kinase 3 (DAPK3), a novel autophagy regulator, may phosphorylate ULK1 and enable it to suppress gastric cancer progression." (PMID 33971627, 2021). "For example, DAPK3 directly phosphorylates Ser556 of ULK1, which increases the activity of ULK1 and promotes the formation of the ULK1 complex, leading to inhibition of the proliferation of gastric cancer cells." (PMID 37143582, 2023). "DAPK3 directly phosphorylates Ser556 of ULK1 to increase ULK1 activity and promote the formation of ULK1 complex, leading to inhibition of the proliferation of gastric cancer cells." (PMID 37143582, 2023). "Our results found that DAPK1/2, but not DAPK3, expression was increased by sodium butyrate treatment in human gastric cancer cells." (PMID 22160140, 2012).
Hypertension (3 papers, 2015 to 2021). The presence of chronic increased pressure in the systemic arterial system. "In the report, the role of DAPK3 in vascular inflammatory responses and development of hypertension was investigated." (PMID 30287790, 2018). "Moreover, it was found that DAPK3 promoted reactive oxygen species (ROS)-dependent vascular inflammation and thereby mediated the development of hypertension in SHR." (PMID 30287790, 2018). "Since SMC migration and vascular remodeling are important processes for the development of hypertension, these data suggest that the DAPK3/p38/HSP27 axis might be a potential pharmaceutical target for the prevention of hypertensive cardiovascular diseases." (PMID 30287790, 2018). "Since DAPK inhibitor blocked the development of hypertension in SHR and vascular inflammation, it was suggested that DAPK3 regulates hypertensive disease through vascular inflammation." (PMID 30287790, 2018).
lung cancer (3 papers, 2016 to 2022). A malignant neoplasm involving the lung. "For example, cells harboring mutated DAPK3 may get chemosensitized with ectopic over-expression of wild type DAPK3 in lung cancer models." (PMID 27126362, 2016).
prostate carcinoma (3 papers, 2016 to 2019). A carcinoma that arises from epithelial cells of the prostate gland. "Additionally, in prostate cancer, an inverse relationship exists between AKT abundance and DAPK3 abundance 53, where Akt inhibition or DAPK3 overexpression in cultured prostate cancer cells reduced proliferation of the cells." (PMID 30548122, 2019). "We believe more specimens may require to understand the role of DAPK-3 in prostate cancer cells, however, it is evident that inhibition of DAPK3 is higher in higher Gleason-score samples in our results." (PMID 27126362, 2016). "It is critical that whether low expression of DAPK-3 in higher Gleason could be due to deletion and mutation of DAPK-3 expression in human prostate cancer specimens." (PMID 27126362, 2016). "ChIPsequencing analyses showed in a prostate cancer cell model that the co-repressor DAXX (death domain associated protein) colocalized with DNMT1 near the TSS (transcriptional start site) of several ATG-related genes including ULK1 and DAPK3 (death-associated protein kinase 3)." (PMID 31861179, 2019).
bladder cancer (2 papers, 2020 to 2022). "Furthermore, we explored the clinical relationship between RBPJ and DAPK3 and found that there was a positive correlation between RBPJ and DAPK3 in renal clear cell carcinoma, bladder cancer, pancreatic cancer, and liver cancer." (PMID 35368029, 2022). "Interestingly, DAPK3, the GMR of NOR, is part of the bladder cancer pathway, and ALG13, the GMR of CWM, is active in the N-glycan biosynthesis." (PMID 33302383, 2020).
breast carcinoma (2 papers, 2017 to 2018). "Sixteen understudied kinases showed strong variance between TNBC and HER2/luminal breast cancer, with higher-ranked understudied kinases being DAPK3, ADCK1, MRCKA (CDC42BPA), STK17A, DMPK and VRK2." (PMID 29643987, 2018). "DAPK3, also called ZIP kinase (ZIPK), has been implicated in interferon γ-and TNFα/Fas-induced cell death and low ZIPK expression was correlated with increased migration and invasion in breast cancer cells." (PMID 28165359, 2017).
epithelial ovarian cancer (2 papers, 2015 to 2021). "It will be very interesting to know if DAPK3 has a role in the miRNA-1307 associated chemoresistance in ovarian cancer." (PMID 25887170, 2015). "In ovarian cancer, miR-1307 was up-regulated in the chemoresistant epithelial ovarian cancer tissues and might play a role in the development of chemoresistance in ovarian cancer by targeting DAPK3." (PMID 34422899, 2021).
liver cancer (2 papers, 2019 to 2022). An epithelial or non-epithelial malignant neoplasm that arises from the liver. "Genes with 5-mC and 5-hmC level changes enriched in these pathways, such as BMP4, HSP90AA1, DAPK3, FADD and CASP8, have been already reported as potential epigenetic biomarkers for liver cancer." (PMID 31337442, 2019).
non-small cell lung carcinoma (2 papers, 2018 to 2023). A group of at least three distinct histological types of lung cancer, including non-small cell squamous cell carcinoma, adenocarcinoma, and large cell carcinoma. "KIAA1429 elevation negatively correlates with tumor suppressor gene DAPK3 expression in non-small cell lung cancer." (PMID 37606975, 2023). "In our previous study, it was demonstrated that knockdown of the DAPK3 gene also blocked non-small cell lung cancer (NSCLC) progression via cellular signaling." (PMID 30287790, 2018).
pancreatic cancer (2 papers, 2018 to 2022). "We also showed that the genes encoding proapoptotic proteins, namely DEDD2, DAPK3, and NLRP1, were overexpressed in pancreatic cancer cell lines treated with AbE." (PMID 30514293, 2018).
renal carcinoma (2 papers, 2022 to 2023). A carcinoma arising from the epithelium of the renal parenchyma or the renal pelvis. "In summary, we not only revealed a novel RBPJ/DAPK3/UBE3A/PBRM1/p21 signaling axis but also identified a combination strategy for overcoming the resistance of renal cancer cells to CDK4/6 inhibitors." (PMID 35368029, 2022). "In summary, our results demonstrate that the RBPJ/DAPK3/UBE3A/PBRM1/p21 signaling pathway regulated the sensitivity of renal cancer cells to CDK4/6 inhibitors." (PMID 35368029, 2022). "At first, reciprocal coimmunoprecipitation assays confirmed the interaction between UBE3A and DAPK3 in 293T and renal cancer cell lines (786-O and ACHN cells)." (PMID 35368029, 2022). "Moreover, the RBPJ/DAPK3/UBE3A/PBRM1/p21 axis induced increased sensitivity of renal cancer cells to CDK4/6 inhibitors." (PMID 37385985, 2023). "Moreover, our data suggest that the RBPJ/DAPK3/UBE3A/PBRM1/p21 axis modulated the sensitivity of renal cancer cells to CDK4/6 inhibitors." (PMID 35368029, 2022). "Therefore, we not only revealed a novel RBPJ/DAPK3/UBE3A/PBRM1/p21 axis but also identified a combination strategy for overcoming the resistance of renal cancer cells to CDK4/6 inhibitors." (PMID 35368029, 2022). "Finally, we demonstrated that the RBPJ/DAPK3/UBE3A/PBRM1/p21 axis contributed to the sensitivity of renal cancer cells to CDK4/6 inhibitors." (PMID 35368029, 2022). "To explore whether DAPK3 destabilized PBRM1 through UBE3A in renal cancer cells, we performed knockdown of DAPK3 and UBE3A alone or in combination in 786-O and ACHN cells." (PMID 35368029, 2022). "However, knocking down RBPJ downregulated the protein and mRNA levels of DAPK3 in renal cancer cells." (PMID 35368029, 2022). "Taken together, these data suggest that RBPJ acts as a transcription factor of DAPK3 and regulates PBRM1 in renal cancer cells." (PMID 35368029, 2022). "Together, these data suggest that DAPK3 is a binding partner of UBE3A and critical for PBRM1 degradation in renal cancer cells." (PMID 35368029, 2022). "Therefore, our results indicate that DAPK3 competes with PKA to bind with UBE3A and enhances the degradation of PBRM1 in renal cancer cells." (PMID 35368029, 2022). "Furthermore, we demonstrated that DAPK3 silencing increased the interaction between PKA and UBE3A, but DAPK3 overexpression disrupted PKA and UBE3A binding in renal cancer cells." (PMID 35368029, 2022). "However, overexpression of DAPK3 strengthened the degradation of PRBM1 induced by UBE3A WT or T508A mutant, which was independent of the kinase activity of DAPK3 in renal cancer cells." (PMID 35368029, 2022).
colorectal cancer (1 paper, 2015). A primary or metastatic malignant neoplasm that affects the colon or rectum. "The frequency of DAPK3 kinase domain mutations in lung, ovary, and colorectal cancer is 3.2% compared to the frequency of 1.4% in all types of cancer, while no DAPK3 mutations have been observed in the corresponding normal tissues." (PMID 25887170, 2015).
diabetic nephropathy (1 paper, 2024). "Notably, SIRT7 and ELK1 mutually inhibit each other at the DAPK3 promoter; thus, forced SIRT7 overexpression may kill the hyperglycemic memory of the ELK1-DAPK3 axis and alleviate diabetic nephropathy." (PMID 37676263, 2024).
glioma (1 paper, 2021). A benign or malignant brain and spinal cord tumor that arises from glial cells (astrocytes, oligodendrocytes, ependymal cells). "A recent study showed that constitutive activation of PI3K and RTK signaling in a glioma cell model in Drosophila led to the activation of Drak, a close relative of the myosin II kinase DAPK3/ZIPK that phosphorylated Sqh, the Drosophila ortholog of myosin II regulatory light chain." (PMID 34071831, 2021).
pancreatic adenocarcinoma (1 paper, 2018). "ADCK1, DAPK3, DMPK STK17A and VRK2 were found to be similarly amplified in other cancers including prostate adenocarcinoma, uterine carcinosarcoma and pancreatic adenocarcinoma." (PMID 29643987, 2018).
preeclampsia (1 paper, 2014). Preeclampsia is a hypertensive disorder of pregnancy that is characterized by new-onset hypertension with proteinuria presenting after 20 weeks of gestation, and depending on mild or severe forms may initially present with severe headache, visual disturbances, and hyperreflexia. "Furthermore, we could find only 5 genes (DAPK3, DUSP1, PAPPA2, ITCH, DENND2D) that overlapped with our gender-specific analysis of our data of all early and late combined preeclampsia samples." (PMID 25247495, 2014).
tumor (32 papers, 2001 to 2025). "Previous studies have shown that DAPK3 is commonly methylated in cancers, resulting in loss of its tumor suppressor function." (PMID 39254643, 2024). "A recent study identified death-associated protein kinase 3 (DAPK3) as a pivotal regulatory complex that drives tumor-intrinsic immunity and immune surveillance through STING-mediated ubiquitination and phosphorylation." (PMID 36231006, 2022). "Previous reports revealed that the DAPK3 promoter is often methylated in various types of cancer, resulting in the loss of its tumor suppressor effect." (PMID 34422899, 2021). "Defining DAPK3 as a tumor suppressor with LOF mutations in cancer patients was one of the first attempts to use bioinformatics to identify functional mutations in a kinase from cancer genomics studies." (PMID 30548122, 2019). "It was reported that the DAPK3 gene is frequently methylated or mutated in various types of cancer, resulting in loss of tumor suppression via DAPK3 in cancer." (PMID 30287790, 2018). "On the other hand, the mutation or deletion of DAPK3 accelerates tumor progression in many cancer types." (PMID 27126362, 2016). "Past studies have shown that the mutations in DAPK3 kinase domain increased the anti-apoptotic and survival abilities of tumor cells and thus reduced the chemosensitivity of tumor cells." (PMID 25887170, 2015). "DAPK3 is proposed to be a tumor suppressor, suggesting that mutations in DAPK3 could result in the loss of function." (PMID 30287790, 2018). "However, DAPK3 loss-of-function has been discovered in several human tumor types, which could help tumor cells evade from host immunity and cancer immunotherapy." (PMID 35603197, 2022). "Inhibiting VIRMA reduces m6A modification on DAPK3 mRNA, thereby enhancing DAPK3 expression and restoring its tumor-suppressive functions." (PMID 40740874, 2025). "Similar to DAPK3, EXT1 is commonly associated with hypermethylated CpG islands, reduced heparan sulfate production, and tumor suppressor‐like functions in various cancers." (PMID 39254643, 2024). "DAPK3 also has kinase independent tumor suppressive function by driving tumor-intrinsic immunity through the STING–IFNβ pathway." (PMID 37414763, 2023). "DAPK3 would induce K63-linked ubiquitination and inhibit K48-linked ubiquitination on STING to induce STING-mediated anti-tumor responses." (PMID 36802409, 2023). "DAPK3 induces K63-linked polyubiquitination of STING by phosphorylating LMO7, which in turn drives tumor-intrinsic innate immunity and tumor immune surveillance." (PMID 37894409, 2023). "These regions contained tumor-related genes, such as Muc16, Pik3, and Bcl2 in amplification regions and Hras, Notch1, Apc2, Ccnd1, Batf2, Dapk3, Smarca4, Traf2, Traf3, Cdk3, and Cdh4 in deletion regions." (PMID 36424557, 2022). "Several studies have suggested a close correlation between kinase and tumor immune, such as tumor suppressor kinase DAPK3 regulating STING-IFN-β pathway to drive tumor-intrinsic immunity." (PMID 36158685, 2022). "DAPK3 is also a potent tumor suppressor, and its functions are compromised during the progression of CaP." (PMID 27126362, 2016). "We demonstrated an inverse correlation between AKT activation and DAPK3 function in preclinical and human tumor tissues." (PMID 27126362, 2016).